INS (insulin)
Diseases named in the same sentence as INS in open-access papers (continued):
Sharing a sentence is not in itself a finding about the gene and the disease.
Insulin resistance (continued). "Meanwhile, adiponectin, an adipose tissue-secreted endogenous insulin sensitizer, was significantly reduced in the HFD-fed mice, in line with the occurrence of insulin resistance, which has been reported in obese mice or humans." (PMID 32244807, 2020). "Hypertrophic adipocytes have a blunted response to insulin and progressively become more lipolytic thereby releasing an excess of NEFA which contributes to systemic insulin resistance." (PMID 33182622, 2020). "One study found that androgens could cause insulin resistance and change insulin action in the target tissues in PCOS patients, which may eventually increase visceral adiposity and reduce the secretion of adiponectin, which is the major insulin-sensitizing adipokine." (PMID 32923930, 2020). "We observed that lower fasting serum insulin (FINS) levels and homeostasis model assessment of the insulin resistance index (HOMA-IR) were reversed by lentivirus-miR-802 compared to merely lentivirus-shFoxo1 treated mice (n = 7)." (PMID 32286278, 2020). "Administration of neferine (5 mg/kg) for 3 weeks via gastrogavage has been reported to decrease fasting blood glucose, insulin, TG, and TNF-α and increase insulin sensitivity in insulin resistance-induced rats." (PMID 33266423, 2020). "Homeostasis model assessment-insulin resistance (HOMA-IR), Quantitative insulin sensitivity checks index (QUICKI), and Body Mass Index (BMI) were computed." (PMID 32863846, 2020). "The ablation of JNK1 in the central nervous system (CNS) reduces body weight, increases insulin sensitivity in the CNS, and neuron-specific JNK1-null mice are protected from HFD-induced glucose intolerance and insulin resistance." (PMID 32183037, 2020). "The comparison of insulin resistance parameters, including HOMA-IR, QUICKI, ISIMatsuda, ISIstumvoll and AUCGlu/AUCIns revealed improvement in insulin sensitivity." (PMID 33117454, 2020). "In consideration of the ever-growing prevalence of obesity and insulin resistance, an increasing interest to the development of new experimental antineoplastic drugs—targeting IGF-1 and/or insulin signaling pathways—are being employed in clinical trials." (PMID 32351453, 2020). "In line with our previous observations in women after delivery, we identified PCS1 and PCS3 as potential predictors for insulin action, whereby PCS3 rather reflects insulin resistance at fasting condition (i.e., the amount of hepatic insulin resistance)." (PMID 32337294, 2020). "Patients with DMII also have elevated insulin and IGF-I due to insulin resistance, which subsequently stimulates cell proliferation and inhibits apoptosis." (PMID 34095407, 2020). "Homeostasis model assessment–insulin resistance (HOMA-IR), insulin sensitivity index (ISI), insulinogenic index (IGI) and disposition index (DI) were all calculated from the Oral Glucose Tolerance Test (OGTT)." (PMID 32731619, 2020). "When the glucose and insulin tolerance tests were performed with HFD-induced obese mice, empagliflozin was observed to improve glucose intolerance and insulin resistance in the fasting and fed states." (PMID 32351447, 2020). "BMI is not only a predicting factor of insulin resistance due to the positive correlations with Homeostatic Model Assessment for Insulin Resistance (HOMA), fast insulin, waist circumference and an inverse relation with HDL cholesterol." (PMID 31947646, 2020). "By the end of treatment (4 weeks), serum blood glucose, homeostasis model assessment insulin resistance (HOMA-IR), insulin, and cardiac enzymes (LDH, CK-MB) were measured." (PMID 32106580, 2020). "The serum adipsin levels might be associated with not only fat insulin resistance, but also potential beta cell function, which is consistent with our result that the serum adipsin level was positively correlated with the CPR-index, a marker of the insulin secretion capacity in T2DM patients." (PMID 33005239, 2020).
Insulin resistance (continued). "The most marked benefits from an active lifestyle were found in relation to fasting insulin and HOMA-IR and highlight the potential of behavioral intervention to prevent development and worsening of insulin resistance." (PMID 32928159, 2020). "Our results provide a novel insight into the molecular mechanisms involved in BBR’s action on insulin resistance and inflammation, and identify adipose tissue SIRT1 as a key regulator of the insulin sensitizing and anti-inflammatory effects of BBR." (PMID 33390968, 2020). "The indices for insulin resistance (HOMA-IR) and insulin secretion (HOMA-β) were significantly different: previously obese women showed higher HOMA-IR and HOMA-β levels." (PMID 32712801, 2020). "Compared with groups B and C, group D had more severe insulin resistance (HOMA-IR) and poorer insulin sensitivity (QUICKI and ISIM)." (PMID 32487177, 2020). "In mice, Pt-PS significantly reduced body weight gain, adipose and hepatic tissues weight, fasting blood glucose, serum insulin, and HOMA-IR score, increased QUICKI value, and regulated insulin resistance-related adipokines." (PMID 32971772, 2020). "By inhibiting insulin-stimulated tyrosine phosphorylation of insulin receptor and insulin receptor substrate-1, TNF-α can play a crucial role in systemic insulin resistance and also decipher a clear link between obesity, insulin resistance and T2D." (PMID 32188105, 2020). "Aging in control mice often leads to obesity and insulin resistance, but GKO and Snell dwarf mice maintain a youthful metabolic state: lean, insulin-sensitive, with high resting metabolic rate." (PMID 32464603, 2020). "HOMA2 is a reliable measure of insulin resistance and the triad of raised fasting insulin, triglycerides and low HDL can reflect an insulin resistant state." (PMID 32339985, 2020). "As we previously demonstrated for WAT hypoxia related to obesity, CIH-induced caveolae disassembly is accompanied by insulin signaling alterations in WAT and systemic insulin resistance in lean mice." (PMID 33324235, 2020). "Despite the elevation of insulin in the sucralose+HFD and sucrose+HFD groups, they showed elevated fasting serum glucose levels, indicating the development of insulin resistance." (PMID 32804018, 2020). "Palmitate attenuated the acute insulin-stimulated increase in the GLUT4 plasma membrane levels, indicating insulin resistance (P+I: 135% ± 10.05% of control, p < 0.05)." (PMID 32664532, 2020). "Another meta-analysis showed that supplementation with probiotic reduced insulin resistance (HOMA-IR) and fasting serum insulin in women with gestational diabetes significantly, as compared to pregnant women with normal glucose tolerance." (PMID 33036170, 2020). "Inflammatory factors can interfere with insulin signaling pathway of IRS/PI3K/Akt and, thus, promote insulin resistance." (PMID 32917052, 2020). "Strikingly, insulin resistance of BMAT observed preoperatively in subjects with T2DM had ameliorated after bariatric surgery and BMAT GU increased significantly upon insulin stimulation also in obese subjects with T2DM (P = 0.043)." (PMID 32311037, 2020). "Enterocytes respond to insulin signals and develop insulin resistance under conditions of obesity-related inflammation, and in particular, it was demonstrated that insulin deprivation reduces small intestinal protein biosynthesis, an effect that could be rescued by insulin treatment." (PMID 33015026, 2020). "A theory has been proposed in which excess FFAs from the highly insulin-resistant visceral adipose tissue (VAT) spill into the liver, leading to excess hepatic adiposity and increased insulin resistance." (PMID 32714070, 2020). "Lastly, we evaluated insulin resistance only by the calculation of HOMA-IR, although the gold standard method for assessment of insulin sensitivity is a hyperinsulinemic-euglycemic clamp study." (PMID 33053742, 2020).
Insulin resistance (continued). "High intermediacy biomarkers of the flow between systems were uric acid, insulin, HbA1c and HDL in the physiological network, while hypertriglyceridemia, insulin resistance, hyperglycemia and high HbA1c were the main intermediaries between pathological states." (PMID 33117199, 2020). "Although we could not directly investigate the association between TyG index and insulin resistance index due to a lack of insulin data in the 2008–2011 KNHANES, we did find that the TyG index was related to the severity of metabolic syndrome, which is closely associated with insulin resistance." (PMID 33222694, 2020). "In addition, irisin was negatively correlated with fasting blood glucose, insulin, insulin resistance, β-cell function and adiposity markers, BMI, and WC, suggesting that elevated irisin could have beneficial effects on regulation glucose, insulin resistance, and obesity." (PMID 32952453, 2020). "Brain insulin resistance is also observed to be developed early in DS subjects, as seen in the inhibition of IRS1 and the uncoupling of downstream elements of insulin signaling." (PMID 32825356, 2020). "Overexpression of NPY in DMH decreased the expression of UCP1 in BAT, leading to insulin resistance; however, the downregulation of DMH NPY improved glucose homeostasis and enhanced insulin sensitivity." (PMID 33123166, 2020). "Chronic inflammation is known to inhibit insulin signaling and to impair GLUT4 translocation to the cell membrane, thereby inducing insulin resistance." (PMID 32023901, 2020). "Insulin and FFA play a central role in metabolic disturbances related to insulin resistance and type 2 diabetes." (PMID 33101209, 2020). "Accordingly, since TAK1 is required for JNK activation, leading to insulin resistance, and since USP18 inhibits TAK-1, an insulin-sensitizing effect of USP18 has been shown in the liver." (PMID 31971958, 2020). "Due to close correlations of glucose tolerance and insulin resistance with the progression of NAFLD, we examined OGTT and plasma insulin to assess the effect of INU on glucose metabolism." (PMID 33390939, 2020). "Increased activation of muscle mTOR by nutrient overload or exposure to high insulin leads to increased serine phosphorylation of IRS-1, impaired insulin signaling and induction of insulin resistance." (PMID 32230718, 2020). "Genetic deletion of GLUT4 from adipose tissue produces a similar degree of whole-body insulin resistance in mice as does the deletion of GLUT4 from skeletal muscle, the tissue responsible for most of insulin-stimulated glucose uptake." (PMID 32911464, 2020). "Recent study have shown that in the presence hyperinsulinemia and insulin resistance, BMD is greater and fracture rate the same as in individuals with preserved insulin sensitivity." (PMID 33033231, 2020). "The body weight, blood lipid, blood glucose, and fasting insulin (FINS) and insulin resistance index (HOMA-IR) were detected and calculated to assess the potential risk of prediabetes." (PMID 32513151, 2020). "The concentration of BDNF correlates positively with immunoreactive insulin and HOMA-IR (homeostatic model assessment for insulin resistance) in women with type 2 diabetes." (PMID 32012942, 2020). "MBH-specific overexpression of SH2B1 substantially ameliorated HFD-induced insulin resistance and glucose intolerance, as assessed by ITT, GTT, and insulin-stimulated phosphorylation of Akt." (PMID 32251290, 2020). "A. pilosa extracts improved insulin resistance in rats fed an HFD, while decreasing blood insulin and HOMA-IR, in our previous study." (PMID 32492866, 2020). "8-week NXT treatment was capable of improving glucose metabolism not only by enhancing insulin resistance, but by lowering fasting serum GLU, fasting INS and HbA1c levels as well (P < 0.05)." (PMID 32616735, 2020).
Insulin resistance (continued). "In vitro study using isolated human adipocytes demonstrated that insulin up-regulates SELENOS expression, thus providing a link between insulin resistance and SELENOS expression in obesity." (PMID 32344656, 2020). "The increased BCAAs correlated with circulating insulin levels, suggesting the elevation of circulating BCAA concentration is a manifestation of insulin resistance." (PMID 32827096, 2020). "Another condition that increases the odds of suffering cardiovascular diseases is type-2 diabetes mellitus, which involves alterations in intestinal sensitivity to insulin and glucagon-like peptide-1 (GLP-1), as does its previous state, insulin resistance." (PMID 32824177, 2020). "On the other hand, non-obese women with GDM have typically a deficiency in insulin production and we hypothesize that lifestyle changes aiming at reducing insulin resistance by increasing physical activity (PA) and improving diet quality might not have similar effect among non-obese and obese women." (PMID 32712801, 2020). "HOMA-IR is used for the assessment of insulin resistance, the increased HOMA-IR has a strong impact on insulin secretion and the progression of DM." (PMID 32498701, 2020). "We determined the insulin sensitivity and found that the rats that were exposed to sucrose during the short-term glucose exposure (SSP) tended to exhibit more insulin resistance than the rats exposed to long-term sucrose (MS)." (PMID 32210194, 2020). "Women with PCOS display insulin resistance in both the fasting (HOMA2-IR) and insulin-stimulated glucose disposal rate (GDR) states compared to BMI-matched normal cycling control subjects." (PMID 32332780, 2020). "hTau mice displayed insulin resistance in the ITT, increased fasting plasma insulin levels and higher HOMA-IR index when compared to WT and TauKO." (PMID 32226410, 2020). "Spontaneous lipolysis was positively correlated with the fasting plasma levels of triglycerides, free fatty acids, insulin, and HOMA-IR as measures of systemic insulin resistance after adjusting for age and sex." (PMID 32180562, 2020). "Although the disposition index remained unchanged, the HOMA-IR index, a measure of insulin-resistance, was decreased by PBI-4547 to the STD group level, suggesting improved insulin sensitivity." (PMID 32728158, 2020). "Meanwhile, ALA significantly reduced the fasting glucose (FG) and fasting insulin (INS) levels, resulting in improved insulin resistance (IR), as suggested by the lower homeostasis model assessment of insulin resistance (HOMA-IR) index." (PMID 33144308, 2020). "The homeostasis model assessment of insulin resistance (HOMA-IR) and the disposition index [(insulinogenic index: I30/G30)/HOMA-IR] were used to calculate insulin resistance and insulin secretion, respectively." (PMID 32407388, 2020). "The prevalence of insulin resistance as per homeostatic model assessment of insulin resistance (HOMA-IR) was estimated and differences between insulin sensitive and insulin resistant were compared." (PMID 32679640, 2020). "We demonstrated that GEP can lower serum glucose and insulin levels and improve glucose and insulin tolerance in HFD-induced obese mice, suggesting that GEP reduced insulin resistance and improved glucose metabolism in the body." (PMID 33142995, 2020). "Similar to NASH patients, impaired insulin sensitivity in GAN DIO-NASH mice was supported by increased HOMA-IR, a widely used index for the estimation of insulin resistance." (PMID 32631250, 2020). "Studies have shown that increased CER levels in skeletal muscle in older individuals can promote insulin resistance, while reducing CER and DAG synthesis can improve skeletal muscle insulin sensitivity." (PMID 32082422, 2020). "Daily intake of spermidine was negatively correlated with BMI, waist circumference and the homeostatic model assessment of insulin resistance (HOMA-IR) index and fasting serum glucose, fasting insulin, and HbA1c levels." (PMID 33151120, 2020).
Insulin resistance (continued). "Insulin resistance can be estimated by several methods, and in the present study it was measured by HOMA-IR, IPITT, and hepatic insulin signaling." (PMID 31275421, 2019). "Dexamethasone (Dex), a glucocorticoid, activates the signaling pathway by inhibiting insulin, thus preventing the transfer of GLUT4, resulting in insulin resistance." (PMID 31355254, 2019). "Undeniably, insulin resistance in T2DM, and the corresponding peripheral hyperinsulinemia, reduces insulin transport through the blood brain barrier (BBB)." (PMID 31428627, 2019). "HOMA-IR is a useful indicator for evaluating insulin resistance, which is calculated by FBS and fasting insulin level." (PMID 31212747, 2019). "Administration of high-fructose-fed (65% kcal/diet) Wistar rats with curcumin (200 mg/kg b.w./day) for 8 weeks resulted in significantly reduced serum glucose, insulin, leptin and TNF-α levels and HOMA-IR, indicating reduced insulin resistance." (PMID 31881654, 2019). "Insulin concentration, HOMA-IR, and prevalence of insulin resistance were significantly increased in subjects across the tertiles of dietary GI." (PMID 31548844, 2019). "Insulin resistance is the main characteristic and influential factor of T2DM, which is characterized by a decrease in the ability of insulin to take up and eliminate glucose from the surrounding tissues, resulting in a disorder of glucose metabolism." (PMID 31555134, 2019). "To better understand the roles played by insulin and TNF-α in insulin resistance, we performed proteomic analysis of differentiated 3T3-L1 adipocytes treated with insulin (Ins), TNF-α (TNF), and both (Ins + TNF)." (PMID 31635166, 2019). "The chronic insulin resistance model shows significant suppression of AKT phosphorylation, suggesting the impairment of proteins in insulin signalling cascade pathways." (PMID 31635074, 2019). "Therefore, although insulin has several functions in the brain, a defect in the effectors of insulin signaling pathway as observed in peripheral insulin resistance may also be responsible for brain insulin resistance." (PMID 31143098, 2019). "Pearson correlation was used to correlate various steady state insulin resistance indices including HOMAIR, HOMA2 index, QUICKI, G/I ratio, HOMA-TG index and serum insulin." (PMID 31223343, 2019). "In the present study, we showed that the SNCA expression was decreased in insulin resistant C2C12 cells and also skeletal muscle tissues of diabetic mice with insulin resistance." (PMID 31827624, 2019). "Retinol-binding protein 4 (RBP4) is a plasma retinoid transporter detected in the early phase of insulin resistance conditions, such as in T2DM and MS; its inhibition allowed an increase in insulin sensitivity in animal trials." (PMID 31658729, 2019). "In suckling piglets and adult rats, IUGR increased serum glucose and insulin concentrations and increased HOMA-IR, indicating the potential presence of insulin resistance." (PMID 31847151, 2019). "Blood glucose, asprosin, irisin, leptin, adiponectin, and insulin were measured before and after 20 WBC treatments, after which a homeostasis model assessment of insulin resistance (HOMA-IR) and atherogenic index of plasma (AIP) were calculated." (PMID 31510055, 2019). "The insulin level was significantly higher in HFD mice than in NFD mice, indicating that insulin resistance was induced in HFD mice." (PMID 31731426, 2019). "Obese mouse models revealed that ER stress contributes to insulin resistance and treatment with TUDCA, a chemical chaperone that enhances protein folding and alleviates ER stress, develops insulin sensitivity." (PMID 31998288, 2019). "The HFFD-feeding induced a significantly elevated serum insulin level and HOMA-IR since week 4, indicating that insulin resistance was developed in model rats." (PMID 31340583, 2019). "OGTT was used to calculate insulin sensitivity (HOMA-S) and insulin resistance (HOMA-IR), defined as HOMA-IR >3." (PMID 30819016, 2019).